YAP1 (Yes1 associated transcriptional regulator)
Diseases named in the same sentence as YAP1 in open-access papers (continued):
Sharing a sentence is not in itself a finding about the gene and the disease.
pancreatic cancer (continued). "Finally, the upregulation of YAP1 expression induced by WDR3 was dependent on an interaction with GATA binding protein 4 (GATA4), the transcription factor of YAP1, which interaction induced the nuclear translocation of GATA4 in pancreatic cancer cells." (PMID 33648545, 2021). "However, the role of the YAP1-TEAD interaction in regulating the expression of target genes in pancreatic cancer has not been completely explored." (PMID 32054505, 2020). "A combined inhibition of YAP1, which is one of the major oncogenic drivers, and its downstream targets such as NMU may be effective to prevent cancer progression and metastasis in pancreatic cancer." (PMID 31575084, 2019). "Collectively, these results suggest that YAP1 binds to KLF5 and promotes the growth of pancreatic cancer cells, independent of TEAD and TAZ, and also indicate that ATF5 enhances the growth of pancreatic cancer cells by suppressing EGR1 expression." (PMID 40124511, 2025). "Although Yap1 is not sufficient for driving de novo pancreatic cancer development, it can drive tumor recurrence in inducible KRASG12D pancreatic cancer models." (PMID 33777798, 2021). "However, these factors are not related to the Wnt-independency phenotype in RNF43-mutant pancreatic cancer, since sgRNAs targeting KDM6A or negative regulators of GLI2 or YAP1, i.e., PTCH1, LATS1, and SAV1, were not enriched in ETC-159 versus vehicle-treated tumors in our initial CRISPR screens." (PMID 35536676, 2022).
ovarian carcinoma (87 papers, 2011 to 2025). A malignant neoplasm originating from the surface ovarian epithelium. "Specifically, YAP1 is implicated in the activation of autophagy and subsequent cisplatin resistance in cases of ovarian cancer." (PMID 37215986, 2023). "The research found that both SNHG6 and Yes-associated protein 1 (YAP1) were significantly upregulated in ovarian cancer tissues compared to adjacent normal tissues, while the expression of miR-543, a known tumor suppressor, was substantially reduced." (PMID 37735423, 2023). "The PKCι/angiomotin/Yes-associated protein 1 (YAP1) signaling pathway plays a critical role in ovarian cancer prognosis." (PMID 36358843, 2022). "The Hippo signaling pathway is altered in ovarian cancer and causes increased nuclear YAP1 and tumorigenesis." (PMID 35820706, 2022). "Because YAP1 is an oncogene in ovarian cancer, and a high YAP1 level is associated with poor ovarian survival in TCGA data, our independent cohort of 157 patients and in an independent study, we characterized YAP1 in more detail." (PMID 27036018, 2016). "Our results suggest that gossypol targets the actin cytoskeletal organization to induce ovarian cancer cell death through changing phosphorylation states of actin-binding proteins and activating YAP1-associated Hippo pathway." (PMID 25180175, 2014). "Specifically, ovarian cancer-secreted exosomal miR-141 activates the Yes-associated protein 1 (YAP1)/Growth-regulated oncogene-alpha (GROα)/Human C-X-C Motif Chemokine Receptors (CXCRs) signaling cascade, thereby enhancing the development of the PMN and ultimately leading to tumor metastasis." (PMID 41179289, 2025). "Similarly, Xia found that YAP-1 expression is associated with poor survival in patients with ovarian cancer and that high YAP-1 expression levels positively correlate with TEAD4 gene expression levels." (PMID 37476371, 2023). "Mechanism experiments, including RNA immunoprecipitation, RNA pull‐down, and luciferase reporter experiments demonstrated that LINC00857 could regulate YAP1 (Yes1 associated transcriptional regulator) by competitively binding to miR‐486‐5p in ovarian cancer." (PMID 32918541, 2020). "Importantly, YAP1 is a bona fide ovarian cancer oncogene, and the expression, activity, and nuclear localization of the YAP1 gene product is associated with aggressive disease and poor prognosis." (PMID 29740072, 2018). "The association of YAP1 with PKCι is also witnessed in ovarian cancer cells." (PMID 30214681, 2018). "In addition, YAP1 overexpression is associated with a poor prognosis in medulloblastomas, colon and ovarian cancer." (PMID 27705928, 2016). "Here, we revealed that the expression of YAP1 was significantly upregulated in ovarian cancer specimens compared to normal tissue." (PMID 39827153, 2025). "Taken together, these results revealed that targeting CK2 significantly suppress ovarian cancer in a YAP1-dependent manner." (PMID 39827153, 2025). "Here, our high-throughput screening reveals that Silmitasertib, a clinically used Casein Kinase II inhibitor, leads to more than 90% decrease of YAP1 protein level and potently suppresses YAP1-driven ovarian cancer progression." (PMID 39827153, 2025). "More importantly, the tight correlation between CK2α and YAP1 was observed in ovarian cancer specimens." (PMID 39827153, 2025). "Although the aberrant upregulation of YAP1 in several cancer types was demonstrated to promote tumor progression, the status and regulatory mechanisms of YAP1 in ovarian cancer are not fully understood." (PMID 39827153, 2025).
ovarian carcinoma (continued). "A molecular mechanism study revealed that exosomal miR‐141 secreted by ovarian cancer cells mediates tumor–stroma interactions, leading to the formation of a tumor‐promoting stromal niche through activation of the YAP1/GROα/CXCRs signaling cascade." (PMID 39968497, 2025). "In this study, we perform a high-throughput screening and identify Casein kinase II (CK2) as an uncharacterized upstream regulator of YAP1 turnover in cancer cells of ovarian cancer and several other cancer types." (PMID 39827153, 2025). "We first analyzed YAP1 expression in ovarian cancer and revealed the significantly upregulated YAP1 expression in ovarian cancer tissues compared to normal tissues." (PMID 39827153, 2025). "Here, our study uncovers a novel tumor-promoting function of DUB3 to stabilize YAP1 in ovarian cancer, which is post-translationally controlled by CK2α." (PMID 39827153, 2025). "Here, we reveal a novel functional role of CK2 to stabilize YAP1 in ovarian cancer and other types of cancer." (PMID 39827153, 2025). "Other studies have shown that in ovarian cancer and small cell lung cancer, activation of YAP1 can lead to cisplatin resistance." (PMID 40918140, 2025). "First, we identify the CK2α-DUB3 axis as an uncharacterized upstream signaling pathway regulating cellular YAP1 abundance in multiple cancer types including ovarian cancer, which critically contributes to tumor progression and chemotherapy resistance." (PMID 39827153, 2025). "Small-molecule inhibitors that directly target YAP1 have been employed as mechanobiological interventions and have demonstrated therapeutic effects in curbing ovarian cancer advancement." (PMID 40822927, 2025). "Within the lipid-rich ascites of ovarian cancer, PUFAs inhibit RhoA-GTPase activity, leading to the downregulation of nuclear YAP1, a critical transcription factor in the Hippo pathway, which dampens antitumor immune responses." (PMID 40330466, 2025). "GROα, which promotes the proliferation and aggression of ovarian cancer cells, was drastically upregulated in primary stromal cells from stromal‐specific Yap1 conditional knockout mice." (PMID 39968497, 2025). "In ovarian cancer, elevated YAP1 expression is correlated with reduced CTL infiltration, indicating a potential role of YAP1 in hindering immune surveillance by modulating the tumor microenvironment." (PMID 39184916, 2024). "For example, Mo exposed that the exosomal miR-141-3p mediated tumor-stroma interactions and cancer metastasis by activating the YAP1/GROα/CXCR signaling cascade in ovarian cancer." (PMID 38845937, 2024). "The YM fusion in ovarian cancer ES-2 cells comprises two functional domains: YAP1 (1–328 aa) and MAML2 (172–1153 aa)." (PMID 39624057, 2024). "Utilizing YM-positive ES-2 ovarian cancer cells as a model, our study demonstrates that the YM fusion acts as an oncogenic driver by activating the YAP1/TEAD transcriptional program, validating the YM fusion as a therapeutic target." (PMID 39624057, 2024). "The persistent YAP1 activation increases ovarian cancer cell proliferation, migration, and resistance to cisplatin-mediated cellular apoptosis." (PMID 38730733, 2024). "Another study showed that YAP1 is both a major effector of miR509-3p-mediated attenuation of migration and invasion, and spheroid formation in ovarian cancer cells." (PMID 37386587, 2023). "In conclusion, the study reveals that SNHG6 plays a role in promoting malignant phenotypes of ovarian cancer cells, and this action is mediated through the miR-543/YAP1 pathway." (PMID 37735423, 2023). "Together, these observations indicate a YAP1 dependency of PVT1 expression with functional correlations in ovarian cancer patients." (PMID 35820706, 2022). "In ovarian cancer, the high expression of YAP1 observed confirmed that miR-513 directly binds to YAP1 and that miR-513 has an inverse relationship with FLVCR1-AS1." (PMID 36649030, 2022).
ovarian carcinoma (continued). "PVT1 is a YAP1 dependent stress responsive lncRNA that promotes ovarian cancer metastasis and chemoresistance, making PVT1 a promising therapeutic target." (PMID 35820706, 2022). "LINC00857 (long intergenic nonprotein-coding RNA857) induces inactivation of the Hippo pathway by competitively binding to miR-486-5p in ovarian cancer and upregulating YAP1 expression, which in turn accelerates ovarian cancer progression and glycolysis." (PMID 36124026, 2022). "Silencing Wnt5A by siRNAs significantly decreased Smad2/3 activation and YAP1 expression and nuclear shuttling in ovarian cancer (OvCa) cells." (PMID 35053353, 2022). "The master regulator, ASCL1, inhibits the activation of YAP1, a transcription factor, that is over-expressed at both mRNA and protein levels in ovarian cancer." (PMID 35052372, 2021). "A recent study revealed the novel mechanism that downregulation of LATS2 resulted in increased YAP1 translocation and up-regulated PD-L1 expression, finally leading to immune suppression in ovarian cancer." (PMID 34699318, 2021). "PRKCI likely inhibits the recruitment of immune cells in the microenvironment of ovarian cancer by regulating the activity of YAP1 through the Hippo signaling pathway, resulting in immunosuppression and promoting tumor growth." (PMID 32993576, 2020). "Taken together, LINC00857 inactivates the Hippo signaling pathway and YAP1 acts as the oncogene in ovarian cancer." (PMID 32918541, 2020). "In a word, this study unveiled that LINC00857 regulates YAP1 by competitively binding to miR‐486‐5p and accelerates ovarian cancer progression." (PMID 32918541, 2020). "First of all, the expression of YAP1 was high in ovarian cancer cells, particularly in SKOV3 and A2780 cells." (PMID 32918541, 2020). "This notion is supported by recent findings that PKCι maintains tumor-initiating cell phenotype, enhances YAP1 activity and augment immune suppression in ovarian cancer." (PMID 32820156, 2020). "In the present study, we found that ASPP2 regulated the expression of aPKC-ι, which has been shown to affect the nuclear localization of the transcription factor YAP1 in ovarian cancer." (PMID 30389910, 2018). "Here, we report that the percentage of nuclear YAP1 expression is significantly higher in metastatic nodules of ovarian cancer patients compared to the matched primary tumor." (PMID 28827520, 2017). "Lastly, overexpression of YAP1 in low-expressing OVCA432 human ovarian cancer cells confirmed the importance of YAP1 for metastasis in vitro as well as in vivo." (PMID 28827520, 2017). "Twenty four hours after transfection of YAP1 siRNA to ovarian cancer cells, platelets were added to the cells that were kept for an additional 72 h under low-attachment conditions." (PMID 28827520, 2017). "In vitro, YAP1 nuclear accumulation resulted in worsening of the malignant phenotype and induced chemotherapy resistance in ovarian cancer cell lines." (PMID 27705928, 2016). "Further, our results suggest that the direct downstream miR-509-3p target YAP1 is likely a critical driver of cellular migration and spheroid formation in ovarian cancers in which levels of YAP1 protein are high." (PMID 27036018, 2016). "In ovarian cancer cell lines, our results established that miR-509-3p can functionally alter YAP1 levels, and can attenuate migration, invasion, and aggregation into 3D spheroids." (PMID 27036018, 2016). "The YAP1 gene is overexpressed in some of the most frequent human tumors such as colon, lung and ovarian cancers." (PMID 27705928, 2016). "The upregulated expression of DUB3 positively correlated with YAP1 in ovarian cancer specimens." (PMID 39827153, 2025). "Whether and how these CK2 substrates besides YAP1 are potentially involved in ovarian cancer progression need further investigation." (PMID 39827153, 2025). "Collectively, we reveal that targeting the CK2α-DUB3 axis might be appealing for suppressing ovarian cancer by destabilizing YAP1." (PMID 39827153, 2025).
ovarian carcinoma (continued). "Furthermore, MYPT1 enhances YAP1 dephosphorylation by interacting with PP1 in ovarian cancer, promoting nuclear translocation and subsequently increasing the expression of pro-survival genes while inhibiting apoptosis." (PMID 40626009, 2025). "We next investigated the role of CK2 on YAP1 turnover and function in ovarian cancer." (PMID 39827153, 2025). "Furthermore, the upregulated expressions of CK2α and DUB3 positively correlate YAP1 expression in ovarian cancer specimens." (PMID 39827153, 2025). "We next investigated whether DUB3 could promote ovarian cancer progression in YAP1-dependent manner." (PMID 39827153, 2025). "Notably, upregulated expressions of CK2α and DUB3 in ovarian cancer positively correlate with YAP1 overexpression." (PMID 39827153, 2025). "YAP1 was expressed highly in ovarian cancer patients with clear cell subtypes of ovarian tumors." (PMID 38730733, 2024). "The YAP1/GROα correlation was demonstrated in clinical samples, highlighting the clinical relevance of this research and providing a potential therapeutic intervention for impeding premetastatic niche formation and metastatic progression of ovarian cancers." (PMID 36624516, 2023). "In ovarian cancer, JADE2 has been shown to be highly overexpressed and may function to regulate YAP1 a critical ovarian cancer oncogene, whilst a gene fusion between JADE2 and NUP98 has been observed in a pediatric acute myeloid leukemia." (PMID 37761019, 2023). "It has been widely recognized that YAP1 mRNA levels are elevated in ovarian cancer." (PMID 37799806, 2023). "In addition, LATS2 interacted with YAP1 and restricted nuclear translocation of YAP1, which enhances transcription activity of PD-L1 and leads to immune escape in ovarian cancer." (PMID 35620733, 2022). "In this paper, we investigate whether Wnt5A is associated with the TGF-β1/Smad2/3 and Hippo-YAP1/TAZ-TEAD pathways, implicated in epithelial to mesenchymal transition (EMT) in epithelial ovarian cancer." (PMID 35053353, 2022). "PKCι inhibition reduces YAP1 nuclear localization and ovarian cancer growth." (PMID 36358843, 2022). "In addition, there is reported evidence that YAP1 signaling, which was activated by FAT1 mutation, can activate EGFR family members though upregulation of their ligands in ovarian cancer, which suggests a potential linkage between YAP1 and EGFR signaling." (PMID 35965328, 2022). "In lung and ovarian cancer cells, YAP1 downregulation enhanced cisplatin sensitivity." (PMID 33420363, 2021). "For instance, YAP1 is targeted by miR-486-5p in ovarian cancer cells." (PMID 33977502, 2021). "Next, we began to investigate the functions of YAP1 in ovarian cancer." (PMID 32918541, 2020). "Overall, LINC00857 regulates YAP1 by competitively binding to miR‐486‐5p in ovarian cancer." (PMID 32918541, 2020). "In conclusion, LINC00857 regulates ovarian cancer progression and glycolysis via sponging miR‐486‐5p to upregulate YAP1 by modulating the Hippo signaling pathway, which may provide the new idea for curing ovarian cancer." (PMID 32918541, 2020). "For example, MLK7‐AS1 regulates the miR‐375/YAP1 axis to promote the progression of ovarian cancer." (PMID 32918541, 2020). "In summary, LINC00857 accelerates ovarian cancer progression and glycolysis via regulating YAP1." (PMID 32918541, 2020). "Moreover, survival analysis evaluating the same set of patient samples indicated that YAP1 protein expression significantly correlated with disease-free survival in ovarian cancer patients." (PMID 28827520, 2017). "To assess whether RhoA might also be involved in the platelet-induced dephosphorylation of YAP1 in detached ovarian cancer cells, we performed RhoA pulldown activation assays in HEYA8 and OVCAR8 cells." (PMID 28827520, 2017). "We suggest that miR-509-3p and drugs that target the miR-509-3p/YAP1/ECM axis may offer novel therapeutic opportunities in ovarian cancer, and potentially in other cancers." (PMID 27036018, 2016).